BRCA1 (BRCA1 DNA repair associated)
Diseases named in the same sentence as BRCA1 in open-access papers (continued):
Sharing a sentence is not in itself a finding about the gene and the disease.
cancer (continued). "This suggests that unresolved R-loops might be the chief source of mutagenesis in cancer when tumor suppressors like BRCA1 are lost." (PMID 30813363, 2019). "Despite this clinical promise, responses to PARPis are not universal, even in cancers carrying BRCA1/2 mutations." (PMID 31266951, 2019). "Understanding of the prevalence and contribution to cancer risk of BRCA1/2 variants in non-European populations has been limited by racial and ethnic disparities in genetic research." (PMID 31892343, 2019). "Moreover, USP9X regulates BRCA1‐mediated HR repair and promotes resistance of cancer cells to DNA‐damaging agents." (PMID 31512408, 2019). "We propose that inhibition of WIP1 may increase sensitivity of BRCA1-proficient cancer cells to olaparib." (PMID 31619012, 2019). "We identified a list of 68,649 candidate allelic variants, which were found in the EVs DNA sample and in the BRCA1-KO fibroblasts exposed to the cancer EVs, but not found in the control BRCA1-KO fibroblast sample." (PMID 31200749, 2019). "Although the clinical benefits of PARP inhibition are clear in BRCA1/2-deficient cancers, tumors with HRR defects in the absence of BRCA gene mutations (i.e., BRCAness) are also responsive to PARP inhibition." (PMID 31552165, 2019). "We showed that cancer patient sera increased the proliferation of BRCA1-KO fibroblasts." (PMID 31200749, 2019). "BRCA1 tumors are more frequently poorly differentiated (grade 3) carcinomas." (PMID 30652428, 2019). "The other seven cancer cases were admitted to be likely sporadic: the other side of the family was not suspicious for cancer heredity, and even when it was (only 1 case) comprehensive BRCA1/2 analysis did not reveal any pathogenic variant." (PMID 29456621, 2018). "Although PARPi therapy has been demonstrated to efficiently sensitize BRCA1/2 mutation-associated cancers and improve survival in patients, not all patients respond to therapy and some patients developed drug resistance after initial favorable response." (PMID 30463359, 2018). "The coding genes affected by this epigenetic lesion cover all the molecular pathways related to cancer biology, such as DNA repair (BRCA1, MHL1 and MGMT), cell cycle (p16INK4a and p15INK4b), apoptosis (DAPK and TMS1) or cell adherence (E-cadherin and cadherin-11)." (PMID 30018746, 2018). "Our finding is in line with the mutation frequency (6%) in non-LS cancer susceptibility genes for individuals undergoing LS genetic testing and 4% of patients with BC tested negative for BRCA1/2 genes." (PMID 29458332, 2018). "It is clear from the genetic data that there are individuals present in the UK10K cohort who have cancer syndromes caused by deleterious mutations (such as BRCA1 nonsense, BRCA2 frameshift and APC frameshift variants)." (PMID 29641532, 2018). "MAF may increase the tumorigenic competence of the BRCA1 defective cancer cells hence leading to rapid metastasis, which makes them a potential target in cancer therapy." (PMID 30224826, 2018). "BRCA1 is a widely studied tumor suppressor gene and it is deregulated in several cancers." (PMID 30322005, 2018). "However, even among women of a given age group, BRCA1-related cancers in particular have been shown to be less mammographically detectable." (PMID 30513626, 2018).
cancer (continued). "Most participants had not heard of genetic testing for cancer risk and those that had did not know about the specific BRCA1/BRCA2 genes." (PMID 30021754, 2018). "Other well-known cancer genes such as BRCA1, CHEK2, JUN, and MYC could also be found in the highly interconnected regions of the PPI network." (PMID 29540752, 2018). "Thus, the loss of proteins favoring DSBs repair via NHE such as 53BP1 or REV7 was identified in different models of olaparib-resistant BRCA1 cancer cell lines and was shown in vitro to promote a competent HR repair." (PMID 30544963, 2018). "From variant analysis of 46 cancer susceptibility genes, we identified 7 pathogenic and likely pathogenic germline variants in 7 genes in 7 (8%) of the 87 patients, namely, MUTYH, RET, TSC2, BRCA1, BRCA2, ERCC2 and HRAS." (PMID 29684080, 2018). "Using cancer-free human breast tissues from BRCA1 mutation carriers and non-carriers, we conducted a genome-wide survey of BRCA1-associated R-loop signals." (PMID 30558184, 2018). "Of importance, those patients who did not meet the established thresholds for BRCA1/2 testing were not spared from relevant cancers, as evidenced by the diagnosis of early asymptomatic cancer in such individuals after the initiation of cancer risk management." (PMID 30646163, 2018). "The women offered the opportunity to participate in this study are not patients with cancer, but rather are healthy premenopausal women who carry a pathogenic mutation in the BRCA1 gene." (PMID 30580266, 2018). "While there has been extensive research on the risk of cancer in women with BRCA1/2 mutations, the cancer characteristics of men with BRCA1/2 mutations have not been well studied." (PMID 29433453, 2018). "The role of BRCA1 in cancer cell metabolism remains to be elucidated, although very recently it has been shown that BRCA1 haploinsufficiency regulates the oxidative mitochondrial metabolism and constitutes an early and important “hit” that drives the tumorigenesis process." (PMID 29584711, 2018). "Significantly, recent metabolic analysis of BRCA1-mutant breast epithelial cells also identified increased BCAA concentrations, suggesting increased BCAA concentrations via reprogramed metabolism may be an early event in BRCA1-cancer development." (PMID 29211698, 2018). "So far, a number of gene- or protein-based cancer biomarkers have been applied to the clinical management of cancer patients with BRCA1/BRCA2 (breast/ovarian cancer), HER-2 (breast cancer), PSA (prostate cancer), and S100 (melanoma) as a few representative examples." (PMID 29527514, 2018). "A subgroup-analysis showedthat this effect was confined only to the BRCA1-wildtype cancers." (PMID 30111871, 2018). "In kindreds carrying path_BRCA1/2 variants, some women in these families will develop cancer despite testing negative for the family’s pathogenic variant." (PMID 29371908, 2018). "The functional biomarker RAD51 enables the identification of PARPi‐sensitive BC and broadens the population who may benefit from this therapy beyond BRCA1/2‐related cancers." (PMID 30377213, 2018). "We thought to screen tumor samples to address whether other DNA repair genes may be related to BRCA1 defective cancers." (PMID 30283497, 2018). "This hypothesis was particularly intriguing, since GPBP1 knockdown caused resistance to BMN673 in BRCA1 mutant cancer cell lines, suggesting that GPBP1 loss may bypass the requirement of BRCA1 for HR." (PMID 29669295, 2018). "Those without BRCA1/2-associated cancer at results disclosure did not have a diagnosis of HBOC syndrome, and long-term risk-reduction measures were recommended." (PMID 30646163, 2018). "In many cancer centres, immediate or post-chemotherapy bilateral mastectomy has become an almost routine recommendation for BRCA1 and BRCA2 mutation carriers regardless of the size or focality of the presenting tumour." (PMID 29337092, 2018).
cancer (continued). "This raises the possibility that PARP inhibitors (PARPi), used to treat BRCA1/2 mutant cancers, could be used to target OS." (PMID 30006631, 2018). "Interestingly, our study emerged that in BRCA1-mutated OC the expression of BRCA1-transcripts was lower, but in contrary those of BRCA2 were significantly higher as compared withBRCA1-wildtype cancers." (PMID 30111871, 2018). "BRCA1 and BRCA2 remain the main candidates for explaining the high risk of cancer in HBOC syndrome." (PMID 30453575, 2018). "A reasonable explanation is that, on average, BRCA2-related cancers (like BRCA1-related cancers) have a faster doubling time than sporadic cancers, which increases their likelihood of presenting as palpable interval cancers rather than being detected on the next round of screening." (PMID 30513626, 2018). "Therefore, mutational status is becoming increasingly important for the management of BRCA related cancers as PARP inhibitors and BRCA1/2 mutation targeting seem to be a hopeful approach for this group of patients." (PMID 30453575, 2018). "Use of PARPi therapy was previously proposed for cancers with BRCA1 methylation." (PMID 30266954, 2018). "Although BRCA1/2-mutated tumors are highly susceptible to platinum drugs and PARP inhibitors, development of resistance poses a major challenge in the clinical management of these cancers and secondary mutations significantly contribute toward this." (PMID 29459887, 2018). "We could not observe a noticeable increase in the proliferative induction on BRCA1 defective cancer cells by BFs or vice versa when co-cultured together." (PMID 30224826, 2018). "Furthermore, predictive testing for family members of women with a pathogenic variant in genes such as the MMR genes, BRCA1/2, RAD51C, RAD51D and BRIP1 provides options for reducing their cancer risk, with screening, surgery or chemoprevention." (PMID 29344385, 2018). "BRCA1 is one of the most studied DNA repair genes, particularly in cancer research." (PMID 30312170, 2018). "Five of the pan-cancer ALFRED genes (BRCA1, ATM, BRCA2, NSD1, and TPCN2) were individually significantly enriched for RDGVs in cases versus controls (P < 0.05 by pan-cancer case-control analysis) with one additional gene, NIPAL3, marginally significant (P = 0.07 by case-control analysis)." (PMID 29973584, 2018). "BRCA1/2 genetic testing in patients with GC with a familial component may help to optimize medical care, including cancer surveillance and the selection of treatment modalities in the era of precision medicine." (PMID 31608315, 2018). "A deficit of BRCA1 is known to play role in cancer development and results in tamoxifen resistance." (PMID 29867779, 2018). "Histologically BRCA1-related cancers are typically cellular and fleshy with round pushing margins (atypical medullary histology), resulting in a more benign mammographic appearance, rather than scirrhous with irregular infiltrating margins like many sporadic cancers." (PMID 30513626, 2018). "All cases included in this study were characterized for BRCA1/2 germline mutations, the major genetic risk factor for MBC, and for the main clinical-pathologic features including: family and personal history of cancer, ER, PR, HER2 and Ki67/MIB1 expression and tumor grade (G)." (PMID 29731982, 2018). "Multiple research laboratories have evaluated these cancer-associated mutations in patients who are negative for BRCA1/2 mutations, but still have a high risk of HBOC." (PMID 29338689, 2018). "In the Italian muticentre HIBCRIT-1 screening study, mammography did not significantly increase cancer detection rates compared to MRI alone for either BRCA1 or BRCA2 mutation carriers." (PMID 30513626, 2018).
cancer (continued). "The identification of path_BRCA1 or path_BRCA2 in an affected BC individual enables access to evidence-based screening for family members, and thus facilitates the implementation of appropriate cancer prevention in these families." (PMID 29371908, 2018). "Previous studies using multigene panel tests identified cancer susceptibility genes in 2.1−16.8% of BRCA1/2 mutation-negative patients." (PMID 29338689, 2018). "Therefore, BRCA1/2-null cancers are more sensitive to platinum-based DNA damaging agents and to PARP inhibitors." (PMID 29882812, 2018). "While DNA damage is not at present a validated biomarker of cancer risk in mutation carriers genomic instability is a well-characterised early hallmark of BRCA1-associated breast tumours." (PMID 30580266, 2018). "Sensitivity to PARP inhibition has been observed in cancers that do not harbor BRCA1/2 deficiencies." (PMID 28314386, 2017). "The evidence that BRCA1-KO fibroblasts can be reprogrammed and turn into several types of cancers by exposing them to only cancer sera, strengthens the hypothesis that metastasis is a pathological process that might not necessarily require transfer of cells." (PMID 28854931, 2017). "Taken together, these data confirm PARP-inhibitor-induced multinucleation in BRCA1- or BRCA2-deficient tumour cells, and suggest that failed mitosis may contribute to the cytotoxicity of PARP inhibition in these cancer cells." (PMID 28714471, 2017). "This synthetic lethality occurs in BRCA1/2 homozygous mutated cancer cells but not BRCA1/2 heterozygous normal tissues, making this a favorable target for potential cancer therapy or preventative treatments." (PMID 29196727, 2017). "The data also suggest that EMSY amplification is a BRCAness feature, and may help to expand the population of patients who could benefit from targeted therapies that are also effective in BRCA1/2-mutant cancers." (PMID 28099152, 2017). "It is well known that inherited and acquired changes in pre-mRNA splicing play a significant role in human disease development and many cancer-associated genes are regulated by alternative splicing, such as CD44, the Wilms' tumor gene WT1, BRCA1, MDM2, FGFR and kallikrein family members." (PMID 29156833, 2017). "In addition to finding an increased number of indels, we found a substantial increase in the number of spontaneously arising base substitutions that resembled a mutation signature associated with BRCA1 and BRCA2 mutant cancers." (PMID 27452521, 2017). "Low or no expression of BRCA1 in cancers is associated with a good clinical response to treatment with platinum therapies and PARP1 inhibitors." (PMID 29021870, 2017). "Altogether theses findings suggest that the newly expressed membrane proteins on both BRCA1-KO fibroblasts and cancer exosomes might have a role in exosomes uptake in target cells." (PMID 28854931, 2017). "Men appear to need help regarding disclosure to children especially boys; to understand BRCA1/2 cancer risks and inheritance patterns; to access information and reassurance from clinicians, while being mindful of men's need to reinstate a sense of their masculine selves." (PMID 28812325, 2017).
cancer (continued). "In the present study, we aimed to accurately analyze the prevalence of mutations in BRCA1, BRCA2 and other cancer-predisposition genes in 272 Taiwanese patients with suspected HBOC based on both a cross-sectional hospital cohort and meta-analysis of published reports." (PMID 28961279, 2017). "PARP inhibitors were developed based on the concept that they could lead cancer cells to apoptosis when the cancer cells lack HR enzymes, including BRCA1/2, PTEN, CtIP and ARID1A." (PMID 29152062, 2017). "Therefore, PARP inhibitors show highly selective synthetic lethality of cells with BRCA1/2-dysfunction cancers." (PMID 28961279, 2017). "PARP1 inhibitors are widely used as drugs that target these BRCA1 and 2-mutant cancers." (PMID 28756516, 2017). "Since it has been reported that CXorf48 enhances the growth of cancer cells by binding to the BRCA1 gene, this gene could also be related to the disease progression of CML patients." (PMID 28862699, 2017). "In order to confirm this view, we sought to verify if the mutation of the BRCA1 oncosuppressor would trigger some membrane changes, which would lead to an active uptake of cancer exosomes as opposed to passive penetration and selective membrane fusion." (PMID 28854931, 2017). "Five-point-five percent 5.5% of these patients displayed somatic alterations classified as 2b, defined as an approved biomarker in another cancer indication and included ERBB2 amplifications, CDK4 amplifications, BRCA1/2 mutations, BRAFV600E mutation and fusion events involving ROS1 and ALK1." (PMID 29156578, 2017). "To determine if the de novo expressed cell receptors after oncosuppressor mutation and the newly identified cancer exosome ligands played a role in the increased cancer exosomes uptake, displayed by BRCA1-KO fibroblasts, we used a panel of pharmacological antagonists." (PMID 28854931, 2017). "Therefore, our data provide a rationale for the use of drugs that increase endogenous acetaldehyde in treatment of BRCA1/2‐compromised cancers, in response to the need for novel effective therapies targeting this tumor subset." (PMID 28729482, 2017). "In addition, BRCA1/2 mutant cancers were found to be selectively sensitive to inhibition of the poly-(ADP)ribose polymerase PARP1 (refs 7, 8, 9)." (PMID 28714471, 2017). "Passive immunization with β-hCG antibodies and/or β-hCG antibodies tagged with anticancer agents may therefore have exciting clinical potential and may give excellent lead for clinicians designing future trials for treating BRCA1 defective cancers." (PMID 28869585, 2017). "Also, germline BRCA1/2 mutations were an independent predictive factor for the development of RDR, while patients harboring germline BRCA1 mutant tumors had worse outcomes to PARP inhibitors relative to patients with BRCA2 mutant cancers." (PMID 29262651, 2017). "A simple multiplex PCR or RNA-sequencing run could harbour enormous predictive value, matching or exceeding the value of traditional biomarkers, for example, prostate specific antigen or BRCA1/2, or histopathological cancer staging." (PMID 28737175, 2017). "Namely, we speculate that therapeutic targeting of splicing factors, including PRPF8 or XAB2, has the potential to disrupt BRCA1 function in cancer cells, which is known to correlate with improved therapeutic response to clastogens." (PMID 29212152, 2017). "BRCA1/2 variants, which are rare and confer high risk of cancer, are not included in the 94-SNP score." (PMID 28830573, 2017).